MIR4708 (microRNA 4708)
Synonyms: hsa-mir-4708; mir-4708
Gene: MicroRNA gene on chromosome 14 (65,335,117 to 65,335,183, reverse strand). Ensembl gene ENSG00000266740.
Homologues: Orthologues: chimpanzee MIR4708 (100% identical).